NQO1 (NAD(P)H quinone dehydrogenase 1)
Diseases named in the same sentence as NQO1 in open-access papers (continued):
Sharing a sentence is not in itself a finding about the gene and the disease.
lung cancer (62 papers, 2011 to 2025). A malignant neoplasm involving the lung. "Upregulated NQO1 expression is associated with the risk of lung cancer but promotes the efficacy of bioreductive anticancer drugs, suggesting the potential of multidrug intermittent therapy." (PMID 39951474, 2025). "It should be noted that hybrids showing the highest activity against the lung cancer cell line (A549) also have an overexpression of the gene encoding the NQO1 protein." (PMID 36234741, 2022). "Several previous studies strongly indicated the association of the variant NQO1 C609T genotypes with lung cancer." (PMID 33313330, 2020). "All these facts and findings encouraged us to evaluate the role of NQO1 C609T polymorphism in CS-related lung cancer (NSCLC) in the Eastern India." (PMID 33313330, 2020). "From the genotypic comparison between the two smoker groups, it was found that a higher risk (OR=1.64, 95% CI: 1.05-2.55, P<0.05) of lung cancer was associated with NQO1 C609T polymorphism." (PMID 33313330, 2020). "This explains the higher risk of developing lung cancer in smokers in the presence of NQO1 C609T polymorphism." (PMID 33313330, 2020). "Our present study on the male current smokers from the Eastern India indicated that the risks of developing lung cancer in association with NQO1 C609T was significant and the odds ratio was greater than one." (PMID 33313330, 2020). "The variant of c.559C > T (p.Pro187Ser) in NQO1 gene decreased the enzymatic activity and increased the risk of lung cancer." (PMID 31207142, 2019). "Several meta-analyses have been performed to obtain a clear correlation between NQO1 C609T and lung cancer risk." (PMID 29254245, 2017). "Epidemiological studies have assessed the correlation between the NQO1 C609T polymorphism and lung cancer risk, but conflicting conclusions remain." (PMID 29254245, 2017). "When we stratified the analysis on the basis of lung cancer subtype, an increased risk of the NQO1 C609T polymorphism on small cell lung cancer was observed." (PMID 29254245, 2017). "In this meta-analysis, we investigated the role of NQO1 C609T polymorphism in lung cancer susceptibility." (PMID 29254245, 2017). "We conducted this updated meta-analysis to identify the function of NQO1 C609T polymorphism in lung cancer risk." (PMID 29254245, 2017). "Numerous studies have investigated the activity of the NQO1 gene C609T polymorphism in lung cancer risk." (PMID 29254245, 2017). "To date, this meta-analysis includes the largest samples used in the investigation of the function of NQO1 C609T in lung cancer susceptibility." (PMID 29254245, 2017). "This polymorphism of NQO1 was reported to be associated with decreased risk of lung cancer for women, especially with light smoking women." (PMID 29221220, 2017). "This updated and comprehensive meta-analysis was performed to better elucidate the correlation between NQO1 C609T polymorphism and lung cancer risk." (PMID 29254245, 2017). "In this study, we first decided to assess the assocation of C609T polymorphism of NQO1 gene with lung cancer risk in a large northeastern Han Chinese population." (PMID 23110137, 2012). "Several individual studies have reported positive signals of NQO1 gene C609T polymorphism with lung cancer; contrastingly, as illustrated in our overall findings among 16453 subjects, there was no detectable risk, even in populations of different descents." (PMID 23110137, 2012). "Subgroup analyses of NQO1 gene 609C/T polymorphism with the risk of lung cancer, and exploration of between-study heterogeneity and publication bias." (PMID 23110137, 2012). "The gene encoding NAD(P)H:quinone oxidoreductase 1 (NQO1) is a promising candidate in the pathogenesis of lung cancer." (PMID 23110137, 2012).
lung cancer (continued). "First, this is to date the largest synthesis exploring the association of NQO1 gene C609T polymorphism with lung cancer." (PMID 23110137, 2012). "Importantly, the cell death induced by β‐Lap and CGA in NQO1‐overexpressing breast or lung cancers is closely linked to autophagy inhibition." (PMID 40014262, 2025). "In a case-control study, it has been indicated that the presence of NQO1*2 allele may be associated with the risk of non-small cell lung carcinoma (the major type of lung cancer) in Indian population." (PMID 33313330, 2020). "Although numerous studies have regarded NQO1 gene C609T polymorphism as a promising candidate for lung cancer, our case-control study in northeastern Han Chinese, along with the meta-analysis, failed to confirm this relation, even across different ethnic populations." (PMID 23110137, 2012). "However, in other studies, the polymorphism of NQO1 is related to the high risk of lung cancer." (PMID 29221220, 2017). "However, the results suggested that NQO1 C609T polymorphism might correlate with lung cancer risk in Caucasians." (PMID 29254245, 2017). "Taken together, these findings suggest that activation of PKA activity by β‐Lap and CGA is crucial for the synergetic induction of apoptotic cell death via autophagy inhibition in breast and lung cancer cells that overexpress NQO1." (PMID 40014262, 2025). "NQO1 is one of the most robustly upregulated molecules in NSCLC cells than benign or even other types of lung cancer cells." (PMID 37305533, 2023). "Adequate findings on COL10A1 and NQO1 in lung cancer have been reported; therefore, HS6ST2 was identified as our gene of interest." (PMID 35260044, 2022). "NQO1 enzyme is a cytosolic reductase that is abnormally overexpressed in multiple cancers, including lung cancer." (PMID 35164213, 2022). "As a transcriptional target of NRF2, upregulated NQO1 can be attenuated by NRF2 blockade to sensitize lung cancer cells to several conventional chemotherapeutic drugs including etoposide, doxorubicin and cisplatin." (PMID 35754474, 2022). "NQO1 is highly expressed in breast and lung cancer tissue and has been described as a potential therapeutic target for NSCLC patients." (PMID 36359002, 2022). "The expression of NQO1 is regulated in cells by KEAP1/Nrf2 pathways, and a series of studies have established prolonged induction of NQO1 expression by ionizing radiation in lung cancer cells and in FSall mice tumors." (PMID 33262939, 2020). "Our study found that UGTA1A, NQO1 and GSTA gene expression levels in lung cancer tissues carrying KEAP1/NRF2 gene mutations significantly increased in comparison with those in lung cancer tissues without KEAP1/NRF2 gene mutations." (PMID 32629428, 2020). "NIR-ASM was successfully used to detect and image the endogenous NQO1 in three live tumor-bearing mouse models (A549 lung cancer, Lewis lung carcinoma, and MDMAMB 231 xenografts) with a high signal-to-low noise ratiometric NIR fluorescence response." (PMID 31189950, 2019). "Tumor cell lines (MC38 colorectal adenocarcinoma, TC-1 lung cancer and Ag104Ld fibrosarcoma) that express a high level of NQO1 were sensitive to β-lap exposure." (PMID 31324798, 2019). "Human lung carcinoma cell line A549 that highly expresses NQO1 was sensitive to β-lap treatment in vitro." (PMID 31324798, 2019). "The NQO1 protein showed a mainly cytoplasmic staining pattern in lung cancer cells, including adenocarcinoma and squamous cell carcinoma (SCC)." (PMID 25880877, 2015). "NQO1 C609T was reported in many diseases, including lung cancer, bladder cancer, and esophageal squamous cell carcinoma." (PMID 26295053, 2015). "IF staining indicated that NQO1 protein was mainly located in the cytoplasm of A549 lung cancer cells." (PMID 25880877, 2015).
lung cancer (continued). "We found that the toxicity of β-lapachone was related to the level of NQO1 expression or activity in lung cancer cells and that high concentrations of β-lapachone killed cells by decreasing phosphorylation of PI3K, AKT, and ERK and activating JNK." (PMID 24505400, 2014). "In this study, we demonstrated that the cytotoxicity of β-lapachone for three different lung cancer cell lines was positively correlated with their NQO1 expression and enzyme activity." (PMID 24505400, 2014). "It has been shown that NQO1 is overexpressed in many human tumors, including cancers of the lung, breasts, liver, esophagus, stomach, colon, pancreas, and bladder." (PMID 22272361, 2012). "Nevertheless, for practical reasons, we hope that this study will not remain just another endpoint of research instead of a beginning to establish the background data to further investigate the molecular mechanisms of NQO1 gene and lung cancer." (PMID 23110137, 2012). "The association between NAD(P)H:quinone oxidoreductase 1 (NQO1) gene C609T polymorphism (rs1800566) and lung cancer has been widely evaluated, and a definitive answer so far is lacking." (PMID 23110137, 2012). "In a number of tumors (e.g., breast, colon, pancreatic, and lung cancers) with high expression levels of NAD(P)H:quinone oxidoreductase (NQO1), β-lapachone activates a novel apoptotic response." (PMID 21936955, 2011). "Interestingly, NQO1 upregulations was already described in many cancers such as pancreatic cancer, uterine cervical cancer, melanoma, and lung cancer." (PMID 39707614, 2025). "PKA activation results in phosphorylation of microtubule‐associated protein 1A/1B‐light chain 3 (LC3) at the serine 12 residue, leading to inhibition of autophagy, which has a substantial impact on cell death induced by β‐Lap in breast and lung cancer cells overexpressing NQO1." (PMID 40014262, 2025). "After a cascade two-step cyclization process with the NQO1 enzyme, the particle size of QPA-P increased and loaded DOX rapidly released into surrounding medium and tumor cells, indicating that NQO1-sensitive micelles were promising for drug delivery in lung cancer." (PMID 35164213, 2022). "Inter and intra-patient heterogenous NQO1 expression was observed in lung cancer." (PMID 36359002, 2022). "Besides, the NQO1-based nanoplatforms also generated increasing attention as NQO1 is upregulated (~2-50-fold) in breast, pancreatic, colorectal, cervical, and lung cancers." (PMID 32641993, 2020). "We found that the NQO1 C609T polymorphism did not correlate with the risk of lung cancer in the overall analysis." (PMID 29254245, 2017). "A variety of case-control studies have been performed to assess the correlation between NQO1 C609T polymorphism and the risk of lung cancer, but an explicit consensus has not been reached." (PMID 29254245, 2017). "The current meta-analysis provides evidence that NQO1 C609T polymorphism is not correlated with lung cancer risk, from the perspective of the former case-control studies." (PMID 29254245, 2017). "Thus, here we performed IF and IHC staining in 150 NSCLC paired with the adjacent non-tumor tissues and 14 normal lung tissues, and found that NQO1 protein localized in the cytoplasm of A549 lung cancer cells and NSCLC tissues." (PMID 25880877, 2015). "In conclusion, sulindac and its metabolites synergistically increase the anticancer effects of β-lapachone primarily by increasing NQO1 activity and expression, and these two drugs may provide a novel combination therapy for lung cancers." (PMID 24505400, 2014). "The catalytic function of NQO1 in the reduction of quinones to hydroquinones is required for the activation of quinone-containing alkylating agents such as mitomycins, an important group of compounds used in the treatment of lung cancer for decades." (PMID 25222473, 2014).
lung cancer (continued). "Our study in northeastern Han Chinese, along with the meta-analysis, failed to confirm the association of NQO1 gene C609T polymorphism with lung cancer risk, even across different ethnic populations." (PMID 23110137, 2012). "In tissues of human lung cancer, NQO1 gene was observed to be over-expressed." (PMID 23110137, 2012). "YEATS4 amplification samples show increased mRNA levels of several well-known antioxidant genes, including NQO1, SLC7A11, and GCLC, suggesting beside NFE2L2 mutation and KEAP1 mutation, YEATS4 amplification could be the other critical genetic marker in lung cancer by modulating antioxidant pathways." (PMID 38514704, 2024). "Importantly, advanced-stage lung cancer cell lines overexpress NQO1." (PMID 35754474, 2022). "Despite some limitations, this meta-analysis indicates that the NQO1 C609T polymorphism may not be associated with lung cancer risk." (PMID 29254245, 2017). "In another subgroup stratified by quality score, we did not detect any correlation between NQO1 C609T and lung cancer risk, yet the T allele acts as a risk factor for lung cancer in low-quality studies under the allele model (T vs. C: OR = 1.12, 95% CI = 1.00–1.20)." (PMID 29254245, 2017). "However, we failed to observe any significant relation between NQO1 C609T and lung cancer risk in the pooled analysis in any of the five genetic models." (PMID 29254245, 2017). "However, some lung cancer cells show lower NQO1 expression or activity and might therefore be resistant to β-lapachone toxicity." (PMID 24505400, 2014). "In addition to reducing the growth of polyps, all three increase NQO1 activity and expression in colon cancer cells, and might therefore be good candidates to increase the cytotoxic effect of β-lapachone against lung cancer cells." (PMID 24505400, 2014). "In order to determine whether NQO1 was a key regulator in β-lapachone-mediated lung cancer cell death, cells were incubated for 6 h with 10 μM dicoumarol, a specific NQO1 inhibitor, and this resulted in about a 67% and 77% reduction in NQO1 activity in CL1-1 and CL1-5 cells, respectively." (PMID 24505400, 2014). "Treatment of ABC1 and SW900 lung cancer cells, which both contain a functional KEAP1-NRF2 response, resulted in significant induction of NRF2 target gene expression, including NQO1, GCLC, HMOX1 and TXNRD1." (PMID 40890297, 2025). "The top five NQO1 mRNA-enriched cell lines in the HPA database were OE19 (Esophageal adenocarcinoma cell line), SiHa (Cervical cancer cell line), A549 (Alveolar cell carcinoma cell line), WM-115 (Melanoma cell line), and LHCN-M2 (Prostate cancer cell line)." (PMID 37583897, 2023). "The induction of Nrf2-target genes NQO1 and Glutathione S Transferase (GST) by ursolic acid inhibited the development of lung cancer in nude mice injected with the lung cancer cells A549." (PMID 29788962, 2018). "Li and colleagues showed that a low methyltransferase EZH2 expression correlates both lung cancer cell lines and tissues with an elevated expression of NRF2, NQO1 (NAD(P)H-quinone oxidoreductase 1), and HO-1 (heme oxygenase 1)." (PMID 29643973, 2018). "Among them, CTNNB1, ZEB1, CDC42, HSP90AA1, BST2, PCNA, and E2F1 have all been shown to promote lung cancer progression, while SAMHD1, HRAS, and NQO1 serve as tumor suppressor genes." (PMID 28498804, 2017). "In lung cancer, 9 genes correlated with poor prognosis, including GCLC, NAD(P)H dehydrogenase (quinone) 1 (NQO1) and thioredoxin (TXN), and 1 with good outcome." (PMID 24342878, 2013). "This study investigated the expression of Nrf2 and of Nrf2-targeted genes (NQO1 and GCLC) and the genes for the metallothionein (MT) isoforms (MT-1A and MT-2A) in human lung cancer and cancer-surrounding tissues." (PMID 23947958, 2013). "Downregulation of MT-1A and MT-2A was found in the surgical stage of lung cancers, whereas the NRF2-targeted gene NQO1 tended to increase." (PMID 23947958, 2013).
lung cancer (continued). "Inter and intra-patient heterogenous NQO1 expression was observed in lung cancer, displaying NQO1 expression are independent of NRF1 and NRF2 in tumors." (PMID 36359002, 2022). "Interestingly, both NQO1 and GSTP1 expression levels were higher in colon and lung cancers as well as compared to the normal tissues, which was also reported in a previous study, though no significant influence on stomach cancer was found." (PMID 33087132, 2020). "Using PCR-RFLP method, we compared the NQO1 C609T genotype distribution in male current smokers with (n=150) and without (n=200) lung cancer." (PMID 33313330, 2020). "As the NQO1 genotypes vary widely among different parts of our nation, it was worthy to check NQO1 C609T status in smokers with or without lung cancer in the Eastern India." (PMID 33313330, 2020). "NQO1 overexpression in tumors but not normal tissue has made it an attractive target for treatment of lung cancer." (PMID 28983331, 2015). "Since NQO1 overexpression has been noted in both non-small cell lung cancer (NSCLC) cell line, β-lapachone could be a potential therapeutic drug for lung cancers." (PMID 24505400, 2014). "Compared with the adjacent non-tumor tissue, the lung cancer tissue showed dramatically higher expression of Nrf2, Mrp1 and NQO1 (compare panel b2 to a2, b3 to a3, b4 to a4)." (PMID 23667609, 2013). "Recent studies report that NQO1 is upregulated in NSCLC in contrast to adjacent non-tumor tissue and is proposed to be a poor prognostic biomarker in stage I-II lung cancer and a potential therapeutic target for NSCLC patients." (PMID 36359002, 2022). "Expression of the Nrf2-targed genes NQO1 and GCLC tended to be higher (30 to 60%) in lung cancers, but was not significantly different from that in peri-cancer tissues." (PMID 23947958, 2013).